OAS1 (2'-5'-oligoadenylate synthetase 1)
Diseases named in the same sentence as OAS1 in open-access papers (continued):
Sharing a sentence is not in itself a finding about the gene and the disease.
COVID-19 (continued). "APOE Ɛ4 allele has been particularly investigated in neurodegenerative and cognitive impairment diseases, and indeed, severe COVID-19 and Alzheimer’s disease share common genetic and metabolic pathways via the OAS1 gene and many risk factors strongly overlap." (PMID 36531241, 2022). "Multi-ancestry fine-mapping of the OAS1/2/3 region shows that a splice site variant in OAS1 is likely responsible for the association of this locus with the risk of severe COVID-19." (PMID 35027740, 2022). "Specific splice variant of OAS1 is likely to be the SNP responsible for the association at this locus, implicating OAS1 as an effector gene influencing COVID-19 severity." (PMID 35956081, 2022). "Next, we explored the functional properties of the OAS1 haplotypes associated with COVID-19 severity." (PMID 35835913, 2022). "Mutations in the OAS1 gene have been identified and one linked to the Neanderthal genome appears to protect from COVID-19 susceptibility and severity." (PMID 35465056, 2022). "By performing a MAGMA gene-level association analysis, we observed that 25 genes including CXCR6, CCR1, IFNAR2, IL10RB, and OAS1 were significantly associated with severe COVID-19 (FDR < 0.05)." (PMID 35172892, 2022). "The OAS1/2/3 cluster has been identified as a risk locus for severe COVID-19 among individuals of European ancestry, with a protective haplotype of approximately 75 kilobases (kb) derived from Neanderthals in the chromosomal region 12q24.13." (PMID 35027740, 2022). "Genetic and functional studies implicate allele-specific regulation of OAS1 splicing and nonsense-mediated decay in COVID-19 severity." (PMID 35835913, 2022). "Supporting this, a recent Mendelian randomization study found that increased circulating levels of OAS1 were associated with reduced risk of very severe COVID-19, hospitalization for COVID-19 and susceptibility to this disease." (PMID 35027740, 2022). "In summary, our search for target genes in the severe COVID-19-risk loci in chromosome 12 revealed three putative causal eGenes that display prominent cell-type-restricted effects—OAS1 in NCM, OAS3 in T-cell subsets, and DTX1 in B cells." (PMID 34799557, 2021). "We propose that the G allele association with protection against severe COVID-19 is explained by the enhanced antiviral activity of OAS1 p46 against SARS-CoV-2, which contributes to early control of viral replication." (PMID 34342578, 2021). "OAS1 expression was readily detectable at the sites of infection in individuals who died of COVID-19, and specific OAS1 alleles are known to be associated with altered susceptibility to infection and severe disease." (PMID 34581622, 2021). "The COVID-19-risk variants in the OAS1/OAS3/OAS2 locus were also associated with reduced expression of OAS3 in certain T cell subsets but not in monocytes, NK cells, or B cells." (PMID 34799557, 2021). "Analysis of the OAS1 transcripts from 499 hospitalized COVID-19 patients revealed that expressing prenylated OAS1 was associated with protection from severe COVID-19." (PMID 34581622, 2021). "Other innate immune genes upstream of OAS1 that are associated with severe COVID-19 in a genome wide association study are IFNAR2, and TYK2, which are in the type I IFN pathway." (PMID 34342578, 2021). "In hospitalized patients, expression of prenylated OAS1 was associated with protection from severe COVID-19, suggesting that this antiviral defense is a major component of a protective antiviral response." (PMID 34581622, 2021). "It had previously been reported that alleles containing a common splice-acceptor single nucleotide polymorphism in OAS1 (Rs10774671) were associated with less severe COVID-19." (PMID 34581622, 2021). "Of the 1031 tests performed, two genes (ABO and OAS1) were significantly associated with COVID-19 related hospitalization (p value <4.85E-5)." (PMID 34315903, 2021).
COVID-19 (continued). "Genomic regions have been associated with COVID-19 susceptibility and outcomes, including the chr12q24.13 locus encoding antiviral proteins OAS1-3." (PMID 34282422, 2021). "SCV2-miR-ORF1ab-2-5p has also been found to mediate allelic differential expression of COVID-19-susceptible gene OAS1." (PMID 35003084, 2021). "It remains unclear whether these findings are generalizable to other populations, such as those of Asian or Latin American descent, where distinct genetic architectures may influence the role of OAS1 variants in COVID-19 susceptibility and severity." (PMID 40543387, 2025). "Therefore, OAS1 is known to be a part of the viral infection response; hence, its recent and robust association with the SARS-CoV-2 virus that causes COVID-19 with minor alleles across the OAS1 haplotype is associated with a less severe response to COVID-19." (PMID 39859237, 2025). "The OAS1/2/3 locus is a highly pleiotropic locus associated with several diseases, including asthma, blood protein measurement, chronic leukemia, systemic lupus erythematosus and severe COVID-19." (PMID 39727170, 2025). "The OAS1 gene, particularly its splice-site single nucleotide polymorphism responsible for producing the p46 isoform, has emerged as a key factor in modulating COVID-19 severity." (PMID 40543387, 2025). "The OAS1/2/3 cluster has been found to be strongly associated with COVID-19 severity." (PMID 38658463, 2024). "Similarly, the OAS1 rs1024611-GG genotype was found to be associated with the severe COVID-19 phenotype in a log-additive genetic model." (PMID 38694517, 2024). "In conclusion, we have used genetic determinants of alternative splicing and COVID-19 outcomes obtained from large-scale studies and found compelling evidence that splicing events in OAS1, ATP11A, DPP9, NPNT, MUC1, and PMF1 have causal effects on COVID-19 severity and susceptibility." (PMID 37794074, 2023). "It is noteworthy that the latest studies show that OAS1 is associated with COVID-19 incidence, so OAS1 may have certain application prospect for clinical evaluations." (PMID 37746262, 2023). "The presence of the A allele in rs10774671 may lead to a decreased expression of OAS1, thereby increasing the specific human risk of developing severe COVID-19." (PMID 37632067, 2023). "A genetic link between risk for Alzheimer’s disease and severe COVID-19 outcomes via the OAS1 gene." (PMID 36845144, 2023). "Furthermore, OAS1/2/3 variation was associated with the risk of developing pneumonia, after adjusting for the other genetic risk factors associated with severe COVID-19 and the main clinical factors associated to complications development in children." (PMID 36873632, 2023). "Notably, allele A OAS1 is associated with severe COVID-19 course (OR = 4.60; 95% CI 1.71–12.37; p = 0.003)." (PMID 37896870, 2023). "Nevertheless, genome-wide association studies have suggested that common variants in the vicinity of OAS1 may be weakly associated with COVID-19 severity." (PMID 36538032, 2023). "Importantly, OAS1 is a potent host antiviral factor that can block SARS-CoV-2 infection in vitro, and OAS1 expression also associates with protection from severe COVID-19 outcome in vivo." (PMID 36757924, 2023). "The results of our study demonstrate the protective effect of GG genotype OAS1 (rs10774671) in a dominant inheritance model of severe COVID-19 (OR = 0.18; p < 0.05), while carriers of allele A showed a higher risk of worse COVID-19 outcome (OR = 5.71; p < 0.05)." (PMID 37896870, 2023). "In addition, exploring diseases associated with OAS1 using OpenTargets revealed that it is primarily linked to COVID-19 and chronic lymphocytic leukemia." (PMID 37928544, 2023). "Since the alternative allele is also a risk allele in COVID-19 GWAS, this implies that these OAS1 RNA splicing isoforms may be associated with impaired OAS1 protein expression and viral clearance in host cells, as previously suggested in other viral diseases." (PMID 37308670, 2023).
COVID-19 (continued). "Further, OAS was identified as a COVID-19 risk locus in association studies suggesting that the splice-site variant at this locus may reduce the enzymatic activity of OAS-1, influencing COVID-19 outcomes." (PMID 36298734, 2022). "Using trans-ancestry fine-mapping approaches in 20,779 hospitalized cases, we demonstrate that this splice variant is likely to be the SNP responsible for the association at this locus, thus strongly implicating OAS1 as an effector gene influencing COVID-19 severity." (PMID 35027740, 2022). "In addition, we analyzed OAS1 haplotypes in association studies with COVID-19 severity and a clinical trial with pegIFN-λ1." (PMID 35835913, 2022). "Recently, a two-sample Mendelian randomization (MR) study revealed that OAS1 could influence the susceptibility and severity of COVID-19." (PMID 36341378, 2022). "Some studies suggest that OAS gene family may provide a potential therapeutic target for COVID-19 if the gene is mutated on chromosome 12q24.13 (a gene cluster that encodes OAS1, OAS2, and OAS3 antiviral restriction enzyme activators)." (PMID 36162993, 2022). "In addition, OAS1 was identified as a putative new risk gene for Alzheimer’s disease, and 4 alleles within OAS1 gene were identified to contribute to both the high incidence of Alzheimer’s disease and critical illness of COVID-19." (PMID 36204639, 2022). "In addition, higher protein expression of histo-blood group ABO system transferase (ABO) and lower protein expression of 2’-5’ oligoadenylate synthetase 1 (OAS1) were also found to be associated with higher risk of COVID-19." (PMID 36583110, 2022). "The OAS1/2/3 cluster has been identified as a risk locus for COVID-19 severity." (PMID 36424512, 2022). "Interestingly, the locus in OAS1/2/3 cluster, which has been associated with severe COVID-19 among individuals of European ancestry, has a protective haplotype of ~75 kilobases (kb) derived from Neanderthals." (PMID 35360730, 2022). "Other genes commonly implicated in coronavirus disease 2019 include ACE2, IL6, DPP9, TYK2, TMPRSS2, FOXP4, and TNF, while the emerging genes consist of FURIN, CXCL10, OAS1, OAS2, OAS3, and ISG15." (PMID 35454970, 2022). "In addition, we found that colocalized severe COVID-19-risk variants in another independent locus (chromosome 12) were also associated with reduced expression of two interferon-inducible genes (OAS1 and OAS3)." (PMID 34799557, 2021). "In this study, we identify a functional OAS1 splice site variant affects COVID-19 outcome." (PMID 34342578, 2021). "The geographical variation in the frequency of alleles encoding prenylated OAS1, such as the high frequency observed in some African populations, could potentially influence the spread and severity of COVID-19." (PMID 34581622, 2021). "Using a proteome-wide ‘colocalisation-first’ approach, we recapitulated previously reported targets (e.g. OAS1) and uncovered additional novel proteins that may play causal roles in COVID-19 susceptibility (THBS3), or severity (FAS)." (PMID 34402426, 2021). "Our analytic approach identified several known targets (e.g. ABO, OAS1), but also nominated new proteins such as soluble Fas (colocalisation probability >0.9, p=1 × 10-4), implicating Fas-mediated apoptosis as a potential target for COVID-19 risk." (PMID 34402426, 2021). "Along these lines, OAS1 levels have been linked to the severity of COVID-19 in other research." (PMID 34581622, 2021). "Importantly, a genetic polymorphisms in OAS1 introduces a variable sensing of dsRNA and influences COVID-19 severity." (PMID 34887937, 2021). "Finally, one protein, called OAS1, formed part of the body’s innate antiviral defence system and appeared to reduce susceptibility to COVID-19." (PMID 34402426, 2021).
COVID-19 (continued). "In the present study, we also found that genetically predicted higher OAS1 – an interferon-induced broad-spectrum antiviral enzyme – was associated with lower risk of both susceptibility and severity of COVID-19, consistent with findings of a recent published report." (PMID 34402426, 2021). "Overall, these results suggest that the pleiotropic association of the OAS1/2/3 locus with multiple diseases, including severe COVID-19, might be explained, at least partially, by transcriptional deregulation of all three OAS genes by regulatory variants lying within the OAS3 Epromoter." (PMID 39727170, 2025). "However, the direction of the eQTL effect was opposite for the two genes: OAS1 gene expression is downregulated by the alternative allele of the COVID-19 GWAS index SNP rs10774671G>A, whereas the expression level of OAS3 gene is upregulated by the alternative allele." (PMID 37308670, 2023). "Specifically, the emergence of derived human-specific alleles rs10774671-A and rs1131454-A might have decreased OAS1 expression compared to all other versions of the gene (ancestral, Neandertal and Denisova), increasing the human-specific risk of severe COVID-19." (PMID 35835913, 2022). "Therefore, this alternative splicing event would change the SNP site rs10774671.This result from CASA is consistent with previous findings that OAS1 splicing pattern was associated with COVID-19 susceptibility and severity, indicating CASA is a reliable and accurate database for AS-related research." (PMID 36266726, 2022). "Despite this, the same variants have effects on gene expression (as assessed in any of several tissues curated by Open Targets Genetics Open Targets Genetics, 2019), which is independent of aptamer binding, suggesting that causal inference regarding OAS1 protein and COVID-19 risk may still be valid." (PMID 34402426, 2021). "OAS1 (2'-5'-oligoadenylate synthetase 1) and OAS3 have been identified through a genome-wide association study as major loci associated with COVID-19." (PMID 41977153, 2026). "Further, OAS-1 expression was raised in LTBi positive COVID-19 group as compared to the LTBi positive HC group (p = 0.019)." (PMID 41468475, 2025). "To assess the contribution of TLR7, TYK2 and OAS1 expression to COVID-19 progression over time, we conducted a longitudinal study on the expression of these three genes in patients with COVID-19." (PMID 41445728, 2025). "The identification of DEGs such as OAS1, APOBEC3A, and IFI44, as well as genes associated with immune responses, highlights the robust activation of antiviral pathways during COVID-19." (PMID 41168347, 2025). "We determined the association between LTBi positivity with severity of COVID-19 as well as mRNA expression of immune related genes including those required for MTB as well as SARS-CoV-2 control; IFN-γ, IFN-α, IL-6, IL-10, OAS1, MAVS, SOCS1 and SOCS3 molecules." (PMID 41468475, 2025). "Elevated IFI44L, ISG15, and OAS1 mirror transcriptomic patterns reported in psoriatic arthritis and severe COVID-19, suggesting convergent antiviral-like activation." (PMID 40869237, 2025). "The top enriched clusters across SARS-CoV-2/COVID-19 studies included genes OAS1-3, IFIT3, SAMHD1, and MX1 involved in the innate immune response, interferon signaling, and defense response to the virus." (PMID 41227320, 2025). "A higher expression of OAS1 (p = 0.019) was observed in LTBi positive COVID-19 as compared with LTBi positive HC groups." (PMID 41468475, 2025). "Beyond this example, colocalization analyses further validated the involvement of IFNAR2 and OAS1–3 genes in COVID-19 physiopathology." (PMID 40208878, 2025). "Reduced severity of COVID-19 and higher OAS-1 gene expression in COVID-19 LTBi positive individuals suggest a protective effect in these individuals." (PMID 41468475, 2025).
COVID-19 (continued). "The activation of interferon-stimulated genes (ISG) such as, 2’-5’-oligoadenylate synthetase (OAS1) and mitochondrial antiviral-signaling protein (MAVS) are associated with mild COVID-19." (PMID 41468475, 2025). "Individuals in the COVID-19 group showed higher expression of OAS1 (p = 0.0002), MAVS (p = 0.0001) and SOCS3 transcripts (p = 0.001) as compared to HC." (PMID 41468475, 2025). "Our results showed that the severe COVID-19 phenotype was associated with the co-occurrence of the CCL2 rs1024611-G, OAS1 rs1024611-A, and DPP9 rs10406145-G alleles." (PMID 38694517, 2024). "In this study, we examined the frequency of three gene variants within the OAS family (OAS1, OAS2, and OAS3) and one in RNASEL, in relation to the manifestation of COVID-19 symptoms and the overall disease prognosis." (PMID 38673053, 2024). "Co-localization analysis identified LZTFL1, MUC4, OAS1, HLA-C, SLC22A31, FDX2, and MAPT as genes involved in COVID-19-mediated causation of MM." (PMID 38400850, 2024). "The distribution of genotypes for the ACE2 rs2074192, IFNAR2 rs2236757, OAS1 rs10774671, and OAS3 rs10735079 polymorphisms conformed to HWE in both the COVID-19 and control groups (p > 0.05)." (PMID 39296547, 2024). "The discovery that a SNP (rs10774671) in OAS1 can exacerbate COVID-19 highlights the important role of genetic variations in OAS1 in influencing disease risk." (PMID 38343534, 2024). "The real association between the CCL2, OAS1, and DPP9 variants and the presence of the severe COVID-19 phenotype was examined using multivariable logistic regression analysis to control the influence of age, sex, obesity, and comorbidities." (PMID 38694517, 2024). "The present study focused on the association between the SNVs CCL2 rs1024611, OAS1 rs10774671, and DPP9 rs10406145 and severe COVID-19 in a population from Quito, Ecuador." (PMID 38694517, 2024). "Analysis of haplotype frequencies revealed that the coexistence of GAG at CCL2, OAS1, and DPP9 variants, respectively, in the same individual increased the presence of the severe COVID-19 phenotype (OR=2.273, 95% CI: 1.271-4.068, P=0.005305)." (PMID 38694517, 2024). "Haplotype frequency analysis revealed that the coexistence of CCL2 rs1024611-G, OAS1 rs10774671-A, and DPP9 rs10406145-G alleles in the same individual increased the presence of the severe COVID-19 phenotype (OR=2.273, 95% CI: 1.271-4.068, P=0.005305)." (PMID 38694517, 2024). "In this study, we analyzed the frequency of three gene variants of OAS (OAS1, OAS2, and OAS3) and one in RNASEL, and evaluated their association with the occurrence of COVID-19 symptoms and disease outcome." (PMID 38673053, 2024). "In a subset of 79 children, a genetic analysis was carried out to evaluate the role of common COVID-19 genetic risk factors (chromosome 3 cluster; ABO-blood group system; FUT2, IFNAR2, OAS1/2/3, and DPP9 loci)." (PMID 36873632, 2023). "Such indicators as male sex, ACE2 rs2074192 allele T, IFNAR2 rs2236757 allele A, OAS1 rs10774671 allele A, CD40 rs4813003 allele C and CASP3 rs113420705 allele C can predict severe COVID-19 course and MIS-C in the pediatric population in 85.6% of cases." (PMID 37896870, 2023). "The variant rs10735079 lies in the interferon-inducible OAS gene cluster (OAS1, OAS2, and OAS3) and was associated with critical COVID-19 illness (P = 1.65 × 10−8) in genome-wide significant associations." (PMID 37745867, 2023). "We have recently identified that a Neanderthal-introgressed isoform of OAS1, which is strongly regulated by an sQTL, protects against COVID-19 severity." (PMID 37794074, 2023). "For instance, an elevated plasma level of 2’-5’-oligoadenylate synthetase 1 (OAS1), involved in viral clearance, has been found to be predictive against severe COVID-19 and influenced by a common haplotype of OAS1." (PMID 38113267, 2023).